EGR1 (early growth response 1)
Diseases named in the same sentence as EGR1 in open-access papers (continued):
Sharing a sentence is not in itself a finding about the gene and the disease.
infection (75 papers, 2010 to 2025). The state of being infected such as from the introduction of a foreign agent such as serum, vaccine, antigenic substance or organism. "Because EGR1 is strongly upregulated in VEEV, EEEV, and RVFV infections, we next sought to see if the loss of EGR1 had any impact on infectious viral titers as compared to wildtype U87MG cells." (PMID 35746681, 2022). "CXCL8 expression was significantly decreased following infection, and the loss of EGR1 resulted in an increase in CXCL8 transcription." (PMID 35746681, 2022). "The top 2 IEGs upregulated in epithelial cells after infection with P. aeruginosa were the genes encoding for the transcription factors EGR1 and c-Fos." (PMID 35508983, 2022). "Additional studies are needed to further elucidate the underlying molecular mechanisms as to how EGR1 contributes to neuronal cell death following infection with VEEV." (PMID 36338037, 2022). "Consistent with our sequencing results, the genetic backgrounds of the egr1 and egr3 alleles were previously noticed to harbor anomalies that led to egr-independent susceptibility to infection by Gram-positive bacteria." (PMID 33127847, 2020). "In order to validate miR-US22 targeting of EGR-1 during infection, a recombinant HCMV construct was designed with mutations in miR-US22 that disrupt the miRNA expression." (PMID 31725809, 2019). "Similar to wild-type BMDCs, nuclear translocation of Egr-1 was observed in MyD88-deficient BMDCs upon infection with T. gondii tachyzoites." (PMID 31681626, 2019). "An analysis of RTA promoter activity during de novo infection of KSHV showed a reduced transcriptional activity of promoter with mutated Egr-1 site as compared to the wild type." (PMID 29207655, 2017). "After analyzing the status of Egr-1 phosphorylation during KSHV de novo infection, we wanted to determine the effect of Egr-1 mutation on RTA promoter activity during KSHV infection." (PMID 29207655, 2017). "Loss of the ability to produce EGR1 resulted in greater cell death at baseline, and this was further increased when infected by WT Salmonella, particularly between 30 min and 120 min post infection." (PMID 41188240, 2025). "Another host factor that may be implicated in enhancing neuronal apoptosis post-infection with VEEV is early growth response 1 (EGR1)." (PMID 40005568, 2025). "Moreover, mutation of the EBS impaired the ability of EGR1 to bind to the viral promoter and resulted in significant reduction in late gene expression and DNA replication during the course of infection." (PMID 36338037, 2022). "Furthermore, Egr-1-deficient mice displayed significantly decreased disease scores from day 2 to day 4 of infection compared to wild-type mice." (PMID 31611276, 2019). "Our study findings provide support for the inhibitory effects of Egr-1 deficiency on cytokine and adhesion molecule production in the brains of mice challenged with meningitic E. coli, which also resulted in a reduction of infection-induced meningeal thickening." (PMID 38233877, 2024). "These transcription factors can dictate infection outcomes, as in the case of Egr1 where it significantly dampens the host inflammatory response." (PMID 41188240, 2025). "EGR1 is a transcription factor widely expressed in the brain and is upregulated post-infection with VEEV as determined via RNAseq." (PMID 40005568, 2025). "Transcriptional upregulation of Egr1 has previously been shown to be largely dependent on bacterial secretion systems in other infection contexts, including those where the bacteria remain extracellular." (PMID 41188240, 2025). "The surge of EGR1 protein abundance during injectisome-mediated infection is driven primarily by translational induction, mediated by the UTRs of the Egr1 mRNA." (PMID 41188240, 2025). "While EGR1 has numerous reported functions in cell differentiation, death, and growth, its role in infection is poorly understood." (PMID 41188240, 2025).
infection (continued). "Through time-resolved parallel transcriptomic and translatomic studies of macrophage infection, we reveal SPI-1 injectisome-dependent infection of macrophages triggers rapid translation of transcription factors, including Early Growth Response 1 (EGR1)." (PMID 41188240, 2025). "Although there was rapid injectisome-dependent transcription of Egr1, there was an even greater induction of its translation, enabling the rapid and robust production of the EGR1 transcription factor early in infection." (PMID 41188240, 2025). "At 60 min post infection, there was a clear increase in both transcription and translation of Egr1 in WT-infected cells." (PMID 41188240, 2025). "We observed that infection of human brain microvascular endothelial cells with meningitic E. coli triggers the activation of early growth response 1 (Egr-1), a host transcriptional activator." (PMID 38233877, 2024). "We compared the regulation of Egr-1 on the TJ proteins, including ZO-1, Occludin, and Claudin-5 in both Egr-1−/− and WT hBMEC in response to the infection." (PMID 38233877, 2024). "By using ELISA, we found that the infection-caused upregulation of VEGFA, PDGFB, and ANGPTL4 in the brains of Egr-1−/− mice significantly decreased compared with that in WT mice." (PMID 38233877, 2024). "EGR1 expression significantly increased 18.5-fold (p < 0.01) at 2 h, peaking at 20.1-fold (p < 0.01) by 4 h post-infection, whilst EGR3 gene expression increased 15.8-fold (p < 0.05) at 2 h, increasing further to 32.5-fold (p < 0.0001) by 4 h post-infection." (PMID 39635778, 2024). "Differences in EGR1 and ATF3 transcriptional response kinetics and magnitude upon infection with different SARS-CoV-2 variants were confirmed via qPCR." (PMID 38305139, 2024). "In the hBMEC model, we found that the mRNA transcription and protein level of Egr-1 showed a significant and time-dependent increase following the infection." (PMID 38233877, 2024). "Although there was reduced expression of EGR1 in response to ece1Δ/Δ and hgc1Δ/Δ infected cells relative to the wild-type infection at 2 h post-infection, there was still a significant increase in EGR1 expression relative to resting cells." (PMID 39635778, 2024). "The infection-induced Egr-1 upregulation in endothelial cells was completely abolished, with no Egr-1 expression in the knockout cells." (PMID 38233877, 2024). "We demonstrate that ERK1/2, NF-κB and the MAP3K Raf1 were indispensable for EGR1 induction during infection, demonstrating for the first time a role for Raf1 signalling in epithelial cell responses to C. albicans infection." (PMID 39635778, 2024). "Further bioinformatics analysis revealed the involvement of Egr-1 in cytoskeletal fiber alterations in hBMEC following infection." (PMID 38233877, 2024). "Crucially, the protein levels of EGR1 produced during infection with both strains followed the same profile and were significantly greater than in resting cells at 2 h post – infection, and not significantly different between strains." (PMID 39635778, 2024). "HK C. albicans elicited production of EGR1 to a similar degree as live infection, as did empty fungal cell walls; the Dectin-1 agonist zymosan." (PMID 39635778, 2024). "Following inhibition of EGFR, EGR1 levels were significantly decreased in response to infection with C. albicans (p < 0.01), treatment with HK yeast (p < 0.05) and zymosan (p < 0.001) after 2 h." (PMID 39635778, 2024). "Infection with both strains resulted in a significant increase in expression of EGR1 as early as 15 min post-infection." (PMID 39635778, 2024). "Meanwhile at the protein level, we observed a significant increase of Egr-1 in the brains of the infected mice that maintained a higher expression in the course of infection." (PMID 38233877, 2024). "In another study, we showed that T. cruzi upregulated the transcript and protein levels of EGR1 in PHCM during the early phase of infection, an observation which is different in parasite challenged PHCF." (PMID 36936778, 2023).
infection (continued). "More recently, EGR1 has been shown to be upregulated at both the mRNA and protein level following infection with HSV-1 in Vero cells." (PMID 36338037, 2022). "To confirm these results, we next generated 293T, HeLa, and HepG2 cell lines stably expressing EGR1 shRNA or control shRNA, using a lentiviral infection system." (PMID 35563324, 2022). "We next examined CHIKV and SINV, both Old World alphaviruses, for EGR1-dependent gene expression post-infection." (PMID 35746681, 2022). "The results indicated that both CHIKV and SINV infection results in an increase (~5-fold over mock and ~2-fold over mock, respectively) in EGR1 expression post-infection, albeit milder as compared to New World alphaviruses." (PMID 35746681, 2022). "CXCL8 expression was significantly decreased following infection and was at least partially dependent on EGR1." (PMID 35746681, 2022). "Other coronaviruses examined, including porcine epidemic diarrhea virus (PEDV), human coronavirus (HCoV)-229E, and HCoV-OC43, were also found to activate EGR1 at both the mRNA and protein level following infection in both H1299 and Vero cells." (PMID 36338037, 2022). "EGR1 was found to be upregulated at both the mRNA and protein level following infection with PEDV in LLC-PK1 cells." (PMID 36338037, 2022). "RNA sequencing of BHV-1 infected MDBK cells identified EGR1 as being differentially expressed and upregulated following infection and EGR1 induction was confirmed at both the mRNA and protein level." (PMID 36338037, 2022). "The transcription factor KLF4 was also significantly induced post-infection and also at least partially transcriptionally dependent on EGR1." (PMID 35746681, 2022). "Infection of EGR1-knockdown cells with HCoV-229E showed significantly reduced detection of viral protein and genomic RNA as well as PARP cleavage." (PMID 35727266, 2022). "Following infection of astrocytes with Zika virus (ZIKV), a flavivirus associated with microcephaly and Guillain–Barré syndrome, EGR1 mRNA is upregulated approximately 2-fold." (PMID 36338037, 2022). "Knockdown of EGR1 in H1299 cells followed by infection with HCoV-229E resulted in significantly reduced VP-1 protein, viral mRNA, and PARP cleavage." (PMID 36338037, 2022). "More recent studies found EGR1 mRNA and protein levels are upregulated following infection with infectious bronchitis virus (IBV) in H1299, Vero, and DF1 cells." (PMID 36338037, 2022). "Apoptosis and impacted viral replication were found to be induced by infection with the Venezuelan equine encephalitis virus; however, knockdown of early growth response 1 (EGR1) significantly inhibited these signaling pathways." (PMID 36093436, 2022). "At 16 h post-infection (hpi), the cells were lysed and the knockdown of EGR1 was confirmed via Western blot." (PMID 35746681, 2022). "EGR1 is upregulated following infection with EV71 in RD and SK-N-SH cells and was found to facilitate viral replication." (PMID 36338037, 2022). "Both the Atf6−/− and PERK−/− cell lines exhibited the same pattern of ERK1/2 phosphorylation and Egr1 accumulation upon T3SS1+ infection as wild-type MEFs, indicating that VopQ’s activation of ERK1/2 was specifically IRE1 dependent." (PMID 33563785, 2021). "The HCMV micro RNA, miR-US22, downregulates EGR-1 during infection, which results in decreased UL138 gene expression." (PMID 32630219, 2020). "EGR-1 is highly expressed during infection in CD34+ HPCs, where is serves to drive UL138 gene expression for latency." (PMID 32630219, 2020). "Further, EGR1 is strongly induced in serum starved, uninfected fibroblasts and infection diminishes this induction by 7-fold." (PMID 31725811, 2019). "Infection with the HCMV ΔmiR-US22 resulted in 2-3-fold increase in EGR-1 protein expression at later time points compared to WT infection in both NHDFs and AECs." (PMID 31725809, 2019).
infection (continued). "In our data set, however, when MYR1 or ASP5 is deleted, EGR1 transcripts actually increase relative to infection with RH-WT, indicating the existence of a more complex level of control of the EGR1 gene via additional effectors." (PMID 29615509, 2018). "We further investigated the progression of a subsequent round of infection performed in BSC40 cells with equal numbers of VACV particles produced in starved WT or egr-1−/− MEFs." (PMID 29561772, 2018). "In this study, we demonstrate that infection of WT MEFs by VACV stimulates a similar pattern of EGR-1 expression through the MEK/ERK pathway." (PMID 29561772, 2018). "In the context of de novo KSHV infection, our analysis reveals that Egr-1 gets phosphorylated after infection of the target cells." (PMID 29207655, 2017). "The expression of RTA, which is regulated through Egr-1, was analyzed at different time intervals (2, 6, 12 and 24h) post-infection." (PMID 29207655, 2017). "The results showed that the infection efficiency of lentivirus Egr1-OE was > 90%, and the cells were in good condition after infection." (PMID 28187447, 2017). "Altogether, these results confirmed that Egr-1 site of RTA promoter is essential for KSHV mediated RTA promoter activation during de novo infection." (PMID 29207655, 2017). "We found a suppression in RTA promoter activity in the target cells with depleted Egr-1 levels after infection." (PMID 29207655, 2017). "Silencing β1-integrins completely inhibited the induction of EGR1 expression after infection with N. meningitidis, S. pyogenes, H. pylori, N. gonorrhoeae, and S. Enteritidis." (PMID 28180113, 2017). "At 2 h post infection, S. pyogenes specifically triggered EGR1 expression in target FaDu cells, whereas after 6 h, EGR1 was unexpectedly induced in AGS cells." (PMID 28180113, 2017). "Only Neisseria gonorrhoeae displayed different time kinetics with the highest EGR1 mRNA levels at 4 h after infection." (PMID 28180113, 2017). "Our results indicated that the abundance of transcripts associated with the interferon and the unfolded protein response pathways was altered following infection and demonstrated that early growth response 1 (EGR1) contributed to VEEV-induced cell death." (PMID 26792742, 2016). "First, Egr-1 is upregulated when EBV interacts with B lymphocytes at the initial infection stage, and constitutive expression of Egr-1 correlates with certain types of EBV latency in B-lymphoid cell lines." (PMID 25834572, 2015). "Recombinant virus A7, nonetheless, was sufficient to produce Egr-1 protein in Vero cells although weaker compared to A4 infection (lane 4)." (PMID 25346859, 2014). "The half-life of endogenous Egr-1 transcript induced by A4 infection is short since very low level of Egr-1 mRNA can be detected at 24hpi." (PMID 25346859, 2014). "Some EGRs, such as EGR1, were modestly or markedly upregulated during a MR infection, though this was due to a secondary transcriptional increase rather than enhanced RNA stability (data not shown)." (PMID 24453974, 2014). "Our results showed that Egr-1 transcript and protein can be generated and accumulated upon infection of recombinant virus in Vero and rabbit corneal cells SIRC." (PMID 25346859, 2014). "The results indicated that a receptor tyrosine kinase inhibitor AG1007 at 1μM exhibited potent inhibition on Egr-1 upon infection." (PMID 25264522, 2013). "To determine if the virus attachment to cells can trigger the synthesis of Egr-1, we performed infections at 4°C followed by Western blot analysis." (PMID 25264522, 2013). "The transcript of Egr-1 reached its peak at 1 hour post-infection (hpi) and quickly declined afterwards (personal observation)." (PMID 25264522, 2013). "UV-inactivated HSV-1 and a recombinant virus over-expressing Egr-1 were generated to evaluate the regulatory effects on viral gene expression and replication during the infection." (PMID 25264522, 2013).
infection (continued). "Infection of SIRC cells indicated that recombinant virus HSV-1/Egr-1 produced a 121-fold increase of Egr-1 compared to the original wild-type virus at 10 hpi." (PMID 25264522, 2013). "Current studies are focusing on if induced Egr-1 by infection can be recruited to HSV-1 promoters during infection." (PMID 25264522, 2013). "It is unclear at this time if the effect of egr-1/pcDNA3.1 over-expression resembles the milieu supporting a lytic infection in vivo." (PMID 22428032, 2012). "This gene is a likely candidate for upregulation by 1 h of infection, as Egr1 is regulated at the transcriptional level, with message levels increasing within 30 min to 2 h after a stimulus." (PMID 23248776, 2012). "For instance, the expression level of EGR-1 significantly decreased in all the infected groups related to un-infections; while compared to the HCV infected groups, it decreased much more in the HIV/HCV co-infected groups." (PMID 23028845, 2012). "These tests revealed a statistically significant 2-fold lower Egr1 expression when YopM was present in the infecting Y. pestis and extended our transcriptional findings from infected mice to an in-vitro infection model." (PMID 23248776, 2012). "With the onset of a primary infection, expression levels of both egr-1 and ORF50 increased up to 6hPI." (PMID 22428032, 2012). "Resveratrol (100 μM) was able to suppress the expression of phospho-ERK1/2 and Egr-1 proteins during de novo infection of cells (lanes 3, 6, and 9)." (PMID 22428032, 2012). "More experiments to determine the role of Egr-1 are underway, especially in other models of infection." (PMID 21619646, 2011). "The recruitment of transcription factors to the Egr-1 promoter during infection was studied by chromatin immunoprecipitation (ChIP)." (PMID 21619646, 2011). "A time-course study revealed that detectable levels of Egr-1 protein were present at 24 hours post infection, and similar levels were detected at 48 and 72 hours post infection." (PMID 21619646, 2011). "Previous studies demonstrated that genes encoding transcription factors such as c-jun, junB, EGR1, and EGR2 were amongst the host genes that were the most rapidly upregulated following infection." (PMID 21479245, 2011). "ChIP assays were performed 24 hours post infection to examine the recruitment of NFкB and pCREB to the Egr1 promoter by HSV-1 infection." (PMID 21619646, 2011). "ChIP assays demonstrated that NFкB and cAMP response element binding protein (CREB) were recruited to the Egr-1 promoter upon infection." (PMID 21619646, 2011). "Egr1 was rapidly and transiently induced at both the transcriptional and translational levels, with mRNA and protein levels peaking at 60 and 120 min post infection respectively, before declining over the remaining timepoints." (PMID 41188240, 2025). "In contrast, infection with the injectisome mutant led to a slight increase in Egr1 mRNA abundance at 60 min, followed by a detectable increase in EGR1 protein by 120 min, with both mRNA and protein at considerably lower levels than in WT Salmonella-infected cells." (PMID 41188240, 2025). "Reverse transcription-coupled quantitative PCR (RT-qPCR) for Egr1 mRNA and immunoblot for EGR1 protein accumulation showed that, during the infection time course, the upregulation was rapid but transient, and that the half-lives of both Egr1 mRNA and its protein product are short." (PMID 41188240, 2025). "Egr1 has previously been reported to be regulated by RNA binding proteins or through sequestration, though the importance of this in macrophages undergoing infection requires further investigation." (PMID 41188240, 2025). "However, little is known about its relevance in epithelial responses to microbes, with only a few studies analysing EGR1 induction upon infection with bacteria or the fungal pathogen Aspergillus fumigatus." (PMID 39635778, 2024).